DIAPH3 (diaphanous related formin 3)
Diseases named in the same sentence as DIAPH3 in open-access papers (continued):
Sharing a sentence is not in itself a finding about the gene and the disease.
cancer (continued). "DIAPH3 expression was found to be significantly higher in almost all tumors than in normal tissues adjacent to cancer, but the available literature revealed that its mode of action varied significantly between different cancers." (PMID 35538918, 2022). "Furthermore, we concentrated on DIAPH3 and concluded that DIAPH3 acts as a cancer suppressor in CRC." (PMID 35538918, 2022). "We observed that DIAPH3 expression is lower in cancer than in normal tissues adjacent to cancer." (PMID 35538918, 2022). "Most reports are of cancers in which the expression of a given formin gene or protein is upregulated, although there are some exceptions, such as the DIAPH3 and FMNL2 proteins, in which the expression is downregulated in triple-negative breast cancer and hepatocellular carcinoma, respectively." (PMID 34685534, 2021). "The inconsistencies of DIAPH3 expression in different cancer types suggest that DIAPH3 may play different roles depending on the type of cancer." (PMID 35201449, 2021). "Many researchers verified that DIAPH3 could regulate growth and migration by affecting cytoskeleton formation in different types of cancer." (PMID 34659408, 2021). "Recently, the roles of DIAPH3 in other cancers have also been reported." (PMID 35201449, 2021). "Therefore, both transgelin and DIAPH3 shared similar biological function of actin-binding to assemble actin cytoskeleton and exhibited opposite clinicopathological relevance between cancer cells and fibroblasts." (PMID 33297976, 2020). "Importantly, mDia2/DIAPH3 overexpression also occurs in numerous other human cancers as revealed by analysis of datasets from The Cancer Genome Atlas (TCGA)." (PMID 32150356, 2020). "DIAPH3 played an important role in the infiltration and metastasis of cancerous cells, which might be a potential therapeutic target for cancer treatment." (PMID 32194788, 2020). "In addition, we expect to develop new therapeutic strategies for cancer treatment by controlling Diaph3 expression levels." (PMID 33187357, 2020). "DIAPH3 plays roles in cancer cell invasion, amoeboid cell behavior, and metastasis in vivo." (PMID 26811494, 2016). "However, the level of expression in tumors is higher, so we investigated whether DIAPH3 is expressed in other cancers with similar conditions." (PMID 35538918, 2022). "However, the role of DIAPH3 in different types of cancer varies." (PMID 35201449, 2021). "Therefore, further investigation of DIAPH3 in other cancers is urgently needed." (PMID 35201449, 2021). "DIAPH3 was identified as a prognostic marker in PDAC fibroblasts using our biomarker screening strategies through the cancer-stromal interaction model, indicating that stromal actin-binding proteins might have an important biological role in cancer progression." (PMID 33297976, 2020). "We verified the four up-regulated lncRNAs (TCONS_00020615, TCONS_00055555, TCONS_00106091, and TCONS_00130858) and eight cancer-related mRNAs (CDCA3, DIAPH3, MCM7, NCAPG2, TPD52, PRC1, SETD6, and KIF22) involved in the ceRNA network by qRT-PCR." (PMID 37098483, 2023). "Cancer cells lacking DIAPH3 displayed an amoeboid phenotype, characterized by rounded cell morphology, high actomyosin contractility, and rapid extension and retraction of membrane protrusions, which allow cells to move rapidly through ECMs." (PMID 39866838, 2025). "Hager and colleagues defined the role of DIAPH3 as a non-canonical regulator of metastasis that restrained conversion to amoeboid cell behavior in multiple cancer types." (PMID 33297976, 2020). "Furthermore, GEO dataset analysis revealed that mDia2/DIAPH3 and INHBA were both overexpressed in the stromal compartment of several cancers in comparison with the respective normal tissue and also in breast CAFs compared to normal breast fibroblasts." (PMID 32150356, 2020).
DIAPH3 also shares sentences with these, for which no sentence is quoted: ovarian cancer (3 papers); Thrombocytopenia (3); anaemia (2); autism spectrum disorder (2); breast tumor (2); colorectal cancer (2); epilepsy (2); Intellectual disability (2); primary ovarian failure (2); acute myeloid leukaemia (1); adenoma (1); age-related hearing loss (1); Anxiety (1); Aphasia (1); Autoimmunity (1); Cardiac disease (1); cardiomyopathy (1); clear renal cell carcinoma (1); diabetes (1); ear tumors (1); Leber congenital amaurosis (1); melanoma (1); metastatic cancers (1); Myelodysplasia (1); myeloid neoplasm (1); neurological disorders (1); osteoarthritis (1); Pancytopenia (1); peripheral neuropathy (1); prostate tumors (1).
A further 2 diseases each share a sentence with DIAPH3 in 1 paper.